CD4 (CD4 molecule)
Diseases named in the same sentence as CD4 in open-access papers (continued):
Sharing a sentence is not in itself a finding about the gene and the disease.
COVID-19 (continued). "Moreover, we identified that the extent of increase in PCGrimAge estimates for participants following COVID-19 was significantly related to blood immune cell compositional changes in CD4 T cells, NK cells, B cells, granulocytes, and plasmablasts." (PMID 35719387, 2022). "Considering the role of humoral immune response in COVID-19 and sarcoidosis, an interesting consideration is offered by the analysis of the behavior of follicular helper T cells (Tfh), a class of CD4+ T cells involved in T-cell-mediated antibody responses and in communication to B cells." (PMID 36148452, 2022). "Interestingly, both antibody and proliferative CD4+ T-cell responses developed at similar levels in post-COVID-19 subjects with pneumonia and vaccinated subjects." (PMID 35744768, 2022). "Moreover, SARS-CoV-2-specific CD4+ T cells in severe COVID-19 patients displayed low antigen avidity and clonality." (PMID 34975340, 2022). "Furthermore, immunization with CD4+ or CD8+ single epitope peptide screened from mice induced CD4+- or CD8+-cell immune responses in mice to protect mice against COVID-19 to a certain degree." (PMID 35891267, 2022). "To define the effects of COVID-19 on the intracellular signaling landscape of circulating leukocytes we measured a panel of signaling phosphoproteins in neutrophils, classical monocytes, NK cells, CD4 and CD8 T cells." (PMID 35421120, 2022). "One theory is that these memory cells experience activation-induced cell death, which is difficult to overcome in the context of lymphopenia.This is in line with our results since we found that patients with severe COVID-19 had a lower proportion of memory CD4+ T cells and of total lymphocytes." (PMID 36045688, 2022). "Moreover, our results showed that the absolute number or frequency of several immune subsets in severe COVID-19 significantly decreased compared to that in mild COVID-19, including CD4 T cells, CD8 T cells, and natural killer cells." (PMID 35573725, 2022). "We observed that late convalescent COVID-19 infected individuals showed higher proportion of CD4+ T cell expressing mono, dual and multi-functional Th1 and Th17 cytokines in response to SARS-CoV-2-specific antigens in comparison to early convalescent COVID-19 infected individuals." (PMID 35336918, 2022). "We found immune response related pathways (TGF-β, IL2-STAT5, IL6-JAK-STAT3, and TNFα signaling, Complement system activation, and Inflammatory response pathway) to be upregulated in the classical monocyte, NK cells, activated CD4+ T cells and CD4+ central memory T cells in active COVID-19 patients." (PMID 36532041, 2022). "In response to SARS-CoV-2 infection, CD4+ T cells can be detected within 2–4 days of symptom onset, and the abundance of these cells are thought to have the strongest correlation with decreased COVID-19 severity." (PMID 36014958, 2022). "For instance, in some more severe COVID-19 cases a dysregulated CD4+ T cell signature may contribute to the greater production of pro-inflammatory cytokines responsible for pathogenic inflammation." (PMID 35833134, 2022). "Additionally, it has been reported that expression level of CD4+FoxP3+CD25+ was significantly decreased in COVID-19 patients, compared with healthy controls." (PMID 35497875, 2022). "Modulation of CD4+ T cell subsets could improve patient outcome in COVID-19, not only by activating the adaptive antiviral immune response, but also, by modulating the aggressive innate inflammatory response." (PMID 36678366, 2022). "Functional clusters identified among Treg cells showed high proportion of cells with simultaneous production of different combinations of TNF-α, IL-2, CD107a, and IFN-γ (which have been found before in the entire population of CD4+ cells) at time-point I in severe post-COVID-19 patients." (PMID 35757700, 2022). "Abundant populations of cytotoxic CD4 have been described in the lungs in COVID-19 patients, where they may participate in viral clearance." (PMID 34931886, 2022).
COVID-19 (continued). "Previous studies have demonstrated that 83% of CD4+ T cells in patients with COVID-19 were S reactive, which could respond to both N and C terminal of S protein." (PMID 36505489, 2022). "In conclusion, the lung parenchyma, airways, and vessels of COPD patients have increased T-lymphocytes with a blunted memory CD4 T cell response and a more invasive SARS-CoV-2 infection pattern and may underlie the higher death toll observed with COVID-19." (PMID 35740993, 2022). "CD4+ T cells can be detected as early as day 2–4 after the onset of COVID-19 symptoms." (PMID 35214700, 2022). "In COVID-19 convalescent patients, memory T cell responses were biased toward CD4+ T cells." (PMID 36437407, 2022). "Together, these observations indicate that male COVID-19 patients with a lethal outcome suffer from a decline in circulating differentiated T helper cells accompanied with a relative enrichment in circulating undifferentiated CD4+ T cells." (PMID 35351135, 2022). "Very early following vaccinia inoculation, many vaccinia-specific CD4 T cells were also CTL, expressing mainly Granzyme K, at day 14, at the same time as the peak of activated CD4 T cells in blood, consistent with what was reported for a COVID-19 patient during the acute phase of the infection." (PMID 36544780, 2022). "Moreover, the intensity of the SARS-CoV-2-specific CD4+ T cell response was also increased in recovered patients who received COVID-19 vaccines." (PMID 36494338, 2022). "We anticipated that all PLWH with CD4 levels <200 cells per μL would be vaccinated by 11 July 2021, because this group is prioritised for vaccination in Spain due to their vulnerability to COVID-19." (PMID 36014083, 2022). "The results might improve the insight of gene expression mechanisms associated with both CD4+ and CD8+ T cells, expand our understanding of COVID-19 and help develop vaccines with long-term protection." (PMID 35601483, 2022). "Collectively, these observations suggest that most of the memory CD4+ T cell response is conserved against SARS-CoV-2 variants of concern, providing an efficacious line of defense that can protect from the development of severe forms of COVID-19." (PMID 35154116, 2022). "It has been noted that COVID-19 patients present the dysregulation of cellular immune response following the pro-inflammatory phase, characterized by sustained and substantial decrease in peripheral lymphocyte counts, specifically CD4+ and CD8+ T cells." (PMID 36290585, 2022). "The authors suggested that the level of CD3+CD4+ T cells could have a predictive value for the early detection of severe COVID-19 forms and the selection of patients requiring rapid aggressive treatment with corticosteroids or IL-6 inhibitors." (PMID 35632823, 2022). "A T cell receptor (TCR)-dependent AIM assay was employed to determine SARS-CoV-2-specific CD4+ T cell responses in recovered COVID-19 patients immunized with COVID-19 vaccines, which has been successfully used to reveal vaccine-specific or virus-specific CD4+ T cells in several studies." (PMID 36494338, 2022). "Similarly in the CD4+ T cell compartment, individuals with moderate COVID-19 patients show TEM TBET+EOMES+ sub-population." (PMID 36369012, 2022). "Moreover, COVID-19 patients have lower levels of Tregs (CD4+CD25+CD127low), especially in severe cases of the disease." (PMID 35497875, 2022). "Thus, IL-6 derived from SARS-CoV-2 specific CD4+ T cells is required for cardiac complications and death in COVID-19 patients with DM." (PMID 36123740, 2022). "For the pairwise comparison between mild and severe COVID-19, 24 studies reported decreased counts for CD4 T-cells in the severe cases compared with mild ones (SMD = −1.39 to −0.11), and only 2 studies reported increased counts for CD4 T-cells (SMD = 0.25 to 0.34)." (PMID 35572964, 2022).
COVID-19 (continued). "It has been well established that infection with SARS-CoV-2 in adults can initiate strong virus-specific adaptive responses, with as high as 100% of adults who have recovered from COVID-19 having detectable memory CD4+ T cell responses and 70% having detectable memory CD8+ T cell responses." (PMID 35044955, 2022). "Indeed, results from several studies indicate that PWH with CD4+ T-cell counts below 500 cells/μl mount weaker responses to the first and second doses of COVID-19 vaccine." (PMID 36545783, 2022). "Dysregulation of CD4 T cell apoptosis in COVID-19 patients helps to explain some recent findings." (PMID 35066575, 2022). "Excluding 24 484 patients with a history of COVID-19, the associations of age, vaccine type, 3-month calendar period, unsuppressed viral load, and CD4 count were similar (data not shown)." (PMID 35671054, 2022). "Here, we examined the effect COVID-19 had on naïve and memory CD4+ and CD8+ T cells." (PMID 36003367, 2022). "Thus, despite the absence of viral infection and higher levels of immune activation (HLA-DR expression), CD4 T cells from COVID-19 patients expressed more Fas/CD95 and Bak transcripts, and are more prone to die compared to HDs." (PMID 35066575, 2022). "However, in comparison to HCs, the percentage of CD4+ T-cells, the CD3++CD4++CD8+/CD3+ ratio, and the CD4+/CD8+ ratio showed progressive increase in COVID-19 patients." (PMID 35422810, 2022). "Additionally, IDE levels in monocytes, CD4+ T-cells, and CD4− T-cells were inversely correlated with circulating insulin levels in COVID-19 patients (both at diagnosis and after hospital discharge)." (PMID 36232381, 2022). "Furthermore, more individuals recovered from severe and critical COVID-19 showed reduced frequencies of central memory (CM) CD4+ and CD8+ T cells (defined as CD45RA−CCR7+CD27+) (Bonferroni-adjusted P-value range 0.02–7.61 × 10−6)." (PMID 36433939, 2022). "Next, we verified the seven peptides with more PBMC samples of convalescent COVID-19 patients and showed that the seven peptides could induce CD4+ IFN-γ+ T-cell and/or CD8+ IFN-γ+ T-cell-positive response." (PMID 35154095, 2022). "This suggest that circulating IL-6 drives CD4 T cell STAT3 activation during acute COVID-19." (PMID 35421120, 2022). "Knowing the significance of CD4+ T cells in anti-viral immunity, examining this adaptive immune cell population will give us more understanding into the type of host responses witnessed in patients with COVID-19." (PMID 35336918, 2022). "Studies have noted that circulating SARS-CoV-2-specific CD8+ and CD4+ T cells existed in 70% and 100% of convalescent COVID-19 patients respectively 45, indicating that almost all SARS-CoV-2 infections elicit the T cell response, especially CD4+ T cell responses." (PMID 34975340, 2022). "In patients with COVID-19, virus-specific CD4+ and CD8+ T cell response (with SARS-CoV-2-conserved T cell epitopes detected in the S1-spike/RBD proteins) has been seen in patients with less severe illness, possibly reflecting cellular immunity suppressing SARS-CoV-2-associated disease." (PMID 36016162, 2022). "However, while some of these studies also reported reduced T cell responses, we found similar CD4+ T cell responses in PLWH vaccinated with an COVID-19 mRNA vaccine." (PMID 36532034, 2022). "Studies indicate a positive relation of the CD4/CD8 ratio with serum phosphate levels in patients with pneumonia which might be consistent with the reduced CD4/CD8 ratio in COVID-19." (PMID 36312855, 2022). "Not surprisingly, IL-33 may play both a deleterious and protective role in COVID-19 by regulating CD4+ T cells." (PMID 36362440, 2022). "In adults and children with severe COVID-19, the proportion of Tregs in CD4+ T was also decreased." (PMID 36505489, 2022). "Therefore, according to data, severe COVID-19 patients consistently had a substantial CD4+ T-cell response against SARS-CoV-2 after 1 month from the onset of the infection." (PMID 36248882, 2022).
COVID-19 (continued). "Early CD4+ responses are associated with milder disease and are more likely to be absent or impaired in severe COVID-19." (PMID 35806161, 2022). "While the decrease in B cell and CD8+ T cell population suggest a decreased MHC Class I mediated antigen presentation, the slight increase of DC and CD4+ T cell populations indicate an elevated MHC Class II mediated antigen presentation in the COVID-19 positive individuals." (PMID 36532041, 2022). "Several reports showed that COVID-19 convalescence may be long and characterized by dysregulation of adaptive immunity, regarding specific CD4+ and CD8+ T cells, that express exhaustion markers for months after symptom onset." (PMID 35757700, 2022). "Furthermore, the lymphocyte CD4+/CD8+ ratio was the highest in the COVID-19 ICU group versus in the control group, which was directly related to the lower CD8+ lymphocyte count among severely ill cases." (PMID 35741107, 2022). "We observed that MKI67-expressing TCR+ T cells within the GEX dividing T/NK cluster were increased in COVID-19 patients, which was further validated by using flow cytometry with the same samples and a different cohort, specifically in CD4+ T cells from progressive patients." (PMID 35064122, 2022). "The efficiency of viral clearance for COVID-19 is significantly affected by CD4+ and CD8+ T cells." (PMID 35955740, 2022). "Specific CD4+ T cells were detected in peripheral blood samples of COVID-19 patients." (PMID 35196808, 2022). "These enhanced expressions could explain partly the lymphopenia observed in COVID-19 as increased PD-1 expression on CD4 + T cells was inversely correlated with decreased CD4 + T lymphocyte count." (PMID 35246776, 2022). "Next, patients with acute COVID-19 had elevated numbers of peripheral blood CD4+ T cells simultaneously producing IL-2 and IL-17 than healthy controls in response to in vitro stimulation with anti-CD3/CD28, pointing to effector Th skewing toward the Th17 phenotype." (PMID 36146622, 2022). "The infiltration of neutrophils, macrophages and CD4+ T lymphocytes in patients with COVID-19 can promote the activation of fibroblasts to myocardial fibroblasts, causing pathological heart remodeling and fibrosis, leading to the development of heart failure and early death of infected patients." (PMID 35387441, 2022). "This suggests that in COVID-19 and aTB there is a distorted hyperinflammatory synergistic state with low immune potential that would alter the polyfunctional capacity and development of CD4-specific T lymphocytes specific against SARS-CoV-2." (PMID 36090983, 2022). "Upon in vitro stimulation with anti-CD3/CD28 antibodies, CD4 T cells of COVID-19 patients showed a lower capacity to express IFNγ and IL-2 and proliferated together with the number of CFSElow cells (a measure of T-cell proliferation) compared to similar T-cell subsets of the control group." (PMID 35632823, 2022). "The probability of survival in ICU-hospitalized patients with COVID-19 decreased significantly in groups with values > 34.3% for CD4+PD-1+ T cells, >20.9% for CD4+PD-L1+ T cells, >19.6% for CD8+PD-1+ T cells, and >20.1% CD8+PD-L1+ T cells at the 14 day time point of hospitalization." (PMID 35741107, 2022). "In addition, using single-cell RNA sequencing, CD8+ and CD4+ T cells were markedly decreased, while B cells were significantly increased during the recovery period of COVID-19." (PMID 35017320, 2022). "However, evaluating the CD4 immunoexpression noted a significantly increased difference in the COVID-19 group." (PMID 36430210, 2022). "Classification rules based on our study demonstrated that a relatively high expression of ITGA6 in CD4+ T cells may indicate COVID-19." (PMID 35928229, 2022). "CD4-mediated SARS-CoV-2 infection of T helper cells may explain the poor adaptive immune response of many COVID-19 patients." (PMID 35419244, 2022).
COVID-19 (continued). "In summary, this study offers a novel view of the mechanisms that might control the development of different CD4+ T cell profiles in the course of pediatric COVID-19." (PMID 35663467, 2022). "Moreover, the T cell response induced by both vaccination and natural infection has been shown able to efficiently recognize the Omicron variant (70−80% of CD4 and CD8 T cells cross-recognize Omicron), thus contributing to the protection from severe COVID-19." (PMID 35995780, 2022). "While not assessed here, additional metrics of high-quality B cell responses following COVID-19, such as somatic hypermutation and memory B cell formation may also be dependent upon coordinated CD4+ T cell responses." (PMID 35857584, 2022). "Whether the high induction of CD4 T-cell responses by the COVID-19 vaccine observed in people with COPD contributes to the protection or poor clinical outcomes upon SARS-CoV-2 infection requires elucidation." (PMID 36560586, 2022). "Cobrotoxin inhibits CD8 T cell proliferation more than that of CD4 T cells, and since COVID-19 cellular immune responses are induced by overexpression and hyperactivation of cytotoxic T lymphocytes, cobrotoxin can restore the CD4/CD8 ratio and perform an immunoprotective activity." (PMID 35273645, 2022). "Other features such as ZFP36L2 in CD4+ T cells can regulate the inflammatory process of COVID-19." (PMID 35928229, 2022). "Both CD4 + and CD8 + T cells demonstrated increased expression of cell surface markers of activation (CD38 + and HLA-DR+) associated with G-MDSCs in children with acute COVID-19 requiring admission to the ICU (r = + 0.63, r = + 0.67, respectively)." (PMID 35733812, 2022). "The relationship between antigen-specific CD4+ T cell responses and COVID-19 severity remains unclear." (PMID 35844575, 2022). "In addition, decreased CD38+HLA-DR− and increased CD38−HLA-DR− CD4 naive T cells occurred in individuals recovered from severe and critical COVID-19 (Bonferroni-adjusted P-value range 0.02–1.46 × 10−4)." (PMID 36433939, 2022). "When malignant tumors appear in the body, the ratio of CD4+/CD8+ also decreases significantly, and lung cancer patients are in a state of immunosuppression, which makes lung cancer patients susceptible to COVID-19." (PMID 36199786, 2022). "Additionally, COVID-19-related disproportion in CD4+ and CD8+ T lymphocytes led to increases in the NLR value, which was reported to be a more sensitive biomarker of inflammation than the individual levels of neutrophils and lymphocytes." (PMID 35453906, 2022). "Above data suggest a gradually compromise of CD4+ T cell responses during COVID-19 progression." (PMID 35909969, 2022). "We observed that regulatory T cells (Treg) and CD4+ naive/terminally differentiated effector memory cell (naïve/TEMRA) populations were somewhat more abundant in the convalescent COVID-19 individuals compared to controls, but these differences were not statistically significant." (PMID 35464396, 2022). "Several meta-analyses suggest that in COVID-19 patients, CD4+ and CD8+ absolute counts may be valuable biomarkers in the prognosis of disease severity and recovery." (PMID 36298626, 2022). "Patients with severe COVID-19 frequently develop CD4+ lymphocytopenia." (PMID 35736068, 2022). "Furthermore, CD38+HLA-DR+ CD4+ T cells were detected at high frequency in COVID-19 respiratory samples than in blood samples." (PMID 35898494, 2022). "Among the COVID-19 cases in recovery period, almost all infections caused by SARS-CoV-2 proteins could initiate CD4+ T immune cell responses." (PMID 35342348, 2022). "Other studies have shown opposing results, indicating that it is unclear whether CD4 count and viral load are indeed factors related to COVID-19 outcomes among PLHIV." (PMID 36192742, 2022).